BDNF (brain derived neurotrophic factor)
Diseases named in the same sentence as BDNF in open-access papers (continued):
Sharing a sentence is not in itself a finding about the gene and the disease.
depression (continued). "Brain-derived neurotrophic factor was also found to promote neuronal survival rate, dendritic growth, spine density, synaptogenesis, and maturation of neurons, all of which are crucial for the development of learning and adaptation processes that are found to be decreased in depression." (PMID 34804417, 2021). "Although BDNF expression requires confirmation in future human studies, these results support the double-hit hypothesis and provide a novel aspect of stress sensitivity in depression pathogenesis." (PMID 34577589, 2021). "CSS significantly reduced the RS-induced anxiety- and depression-like behaviors and hippocampal NF-κB activation and IL-6 expression, blood corticosterone level, and colonic IL-6 expression and myeloperoxidase activity, while the RS-suppressed BDNF expression increased." (PMID 34391441, 2021). "Finally, as far as we know, no previous study evaluated the effects of WBVT on blood BDNF levels and crucial clinical (e.g., sleep quality and depression screening) symptoms associated with the biological rhythms in women with FMS." (PMID 34900203, 2021). "A reduction in BDNF serum levels has been seen in patients diagnosed with MDD, which implies a role for BDNF in the pathology of depression." (PMID 34358084, 2021). "Therefore, Pdcd4 is a typical molecule therapeutic target for depression and silencing Pdcd4 could specifically elevated BDNF expression at translational level." (PMID 34772918, 2021). "Therefore, enhancing the expression of BDNF is an important strategy for depression therapy." (PMID 34772918, 2021). "Moreover, recent studies suggest that the brain-derived neurotrophic factor- (BDNF-) mammalian target of rapamycin complex-1 (mTORC1) signaling pathway is a crucial target pathway for improving depression and mediates the rapid antidepressant-like effects of various antidepressants." (PMID 33628219, 2021). "Therefore, it is likely that the communication between Keap1–Nrf2 signaling and BDNF–TrkB signaling in the brain might play a crucial role in depression." (PMID 33627628, 2021). "However, there are controversial reports about the effects of BDNF on depression." (PMID 33801688, 2021). "Depression is also accompanied by altered hippocampal or frontal brain structures and it has been consistently suggested that this might be a consequence of lowered BDNF." (PMID 34299103, 2021). "However, results concerning the methylation of BDNF and its role in depression have been ambiguous." (PMID 34970165, 2021). "Thus, dysregulation of BDNF presumably could lead to resistance to leptin, contributing to the pathogenesis of depression and Alzheimer’s disease." (PMID 33106599, 2021). "Therefore, promoting BDNF expression provides a strategy for the treatment of depression." (PMID 34772918, 2021). "Interestingly, the authors found a sex-specific relationship between BDNF and microglial inflammatory biomarkers, a mechanism that could become very important for sex differences in depression." (PMID 34938182, 2021). "Symptoms of depression have been associated with lower serum BDNF in non-pregnant adults." (PMID 33462179, 2021). "Indeed, the relationship between circulating platelets and BDNF is impacted by more than platelet count per se, as aspects of platelet function are altered by passive heating in humans or in pathological states like major depressive disorder." (PMID 34882699, 2021). "Thus, not just BDNF, but related genes are dysregulated in the depression portrait and identification of these associated genes can improve our understanding of how this pathway is disrupted." (PMID 33589676, 2021). "Indeed, the Val66 (Val/Val) BDNF prodomain ligand facilitates long-term depression in the hippocampus, which may have implications for neurocognitive, appetitive and metabolic disorders." (PMID 34867148, 2021). "This study suggests that BDNF may be an effective biomarker for the treatment of depression." (PMID 34588957, 2021).
depression (continued). "The association of growth factors, especially BDNF, with MDD is often indicated in the literature, and the likely mechanism by which SARS-CoV-2 could reduce it may prove it to be a good biomarker of post-COVID depression." (PMID 34575258, 2021). "GSB-106, developed as a small dimeric dipeptide mimetic of BDNF, was previously shown to produce antidepressant-like effects in the mouse Porsolt test, tail suspension test, Nomura water wheel test, in the chronic social defeat stress model and in the inflammation-induced model of depression." (PMID 34948177, 2021). "Thus, some scientists consider BDNF and BDNF promoter methylation to be biomarkers for depression." (PMID 33926511, 2021). "Moreover, in patients with depression, there was a significant decrease in BNDF protein levels compared to controls, while administration of antidepressants, such as selective serotonin reuptake inhibitors, stimulated BDNF expression and reversed the symptoms of depression." (PMID 34073101, 2021). "Along with changes resulting from reduced levels of estrogen, age-related changes in the brain such as decreased expression of brain-derived neurotrophic factor (BDNF) and hippocampal atrophy may be important mechanisms that predispose middle-aged women to depression." (PMID 35002797, 2021). "Here, in a clinical observation of the effect of low dose of Yueju pill treatment, we disclosed that the ratio of serum BDNF level to the scale of depression using the scores of HAMD-24, defined as neuroplasticity index (NI), may be useful for prediction of the antidepressant treatment outcome." (PMID 34776888, 2021). "Although the role of BDNF in depressive behavior is yet to be clearly understood, the potential role of BDNF in neuronal plasticity, dendrite development, and modulation of depressive behaviors makes it a reliable therapeutic target in the treatment of depressive disorders." (PMID 33833828, 2021). "Thus, the antidepressant properties of both these compounds can be attributed to their ability to influence 5‐HT and BDNF pathway, and thereby suggesting that this combination strategy can definitely act as alternative therapy for depression disorder with very limited side effects." (PMID 33598202, 2021). "Moreover, central administration BDNF may reduce depressive symptoms, while conditional BDNF knockout in animals produces depression-like effects." (PMID 32513185, 2020). "Additionally, inhibition of miR-124 may be a strategy for treating depression by activating the BDNF-TrkB signalling pathway in the hippocampus." (PMID 33029119, 2020). "The association between BDNF and anhedonia levels in absence of an association between BDNF and general depression severity could indicate that in our comorbid sample anhedonia might indeed have been the most affected symptom domain of depression." (PMID 32372985, 2020). "Since low BDNF levels were associated with self-reported anhedonia across conditions, future studies might further explore anhedonia as a transdiagnostic symptom in AUD and depression." (PMID 32372985, 2020). "It is also worth mentioning that low serum levels of BDNF have been found to be a characteristic of depression; in this regard, one could expect that after an intervention with a positive effect on depressive symptoms (as it was the case of MAIR), increases in BDNF levels should be observed." (PMID 33050630, 2020). "Hence, the BDNF imbalance expression in the brain may help to clarify the relationship between neuroplasticity and the pathophysiology of depression." (PMID 33029119, 2020). "Since the synthetic sites of BDNF in the central region of hippocampus are mainly in the CA1, CA3, and the hilus of dentate gyrus, it is proposed that induction of the proliferation of endogenous neural stem cells and upregulation of BDNF may be a new strategy for the treatment of depression." (PMID 32982748, 2020). "BDNF could intermediate between depression and the level of disability after stroke." (PMID 33213019, 2020).
depression (continued). "In addition, impairments in proper BDNF expression are similarly noted in both depression and AD." (PMID 31951614, 2020). "Additionally, our previous study showed a correlation of BDNF and depression in patients with FMS." (PMID 32859253, 2020). "As support by current evidence, BDNF plays a key role in the pathophysiology of major depression through neuroplasticity and neurogenesis and is at the base of the classic neurotrophic hypothesis of depression." (PMID 32033608, 2020). "The neurotrophic factor and neurogenesis hypotheses connect BDNF with plasticity and depression." (PMID 33293948, 2020). "Therefore, future studies will still need to measure the changes in BDNF in the comorbidity models to further clarify whether BDNF has similar changes with addiction and depression models." (PMID 32694984, 2020). "Importantly, these epigenetic mechanisms may be involved in the role of BDNF in depression and response to antidepressants." (PMID 33331415, 2020). "Taken together, we found that both CSS and coadministration of CSS and FLU can relieve and improve the depression-like behavior and cognitive function, which may be due to the regulation of the BDNF/ERK/CREB signaling pathway in the hippocampus and frontal cortex." (PMID 32185198, 2020). "One of the hypotheses of depression proposes a role for BDNF in the etiology of the pathology, and it has been demonstrated that depressed patients have lower BDNF levels both in serum and in the prefrontal cortex (PFC) and hippocampus (Hip) with respect to healthy subjects." (PMID 32872446, 2020). "However, given the critical need for biomarkers in the field of depression, the potential ability to correlate BDNF plasma levels with antidepressant responses to ketamine may warrant further investigation." (PMID 32351365, 2020). "Furthermore, several signaling pathways involved in the regulations of oxidative stress, neuroinflammation, neurotransmitter dysfunction, and neurotrophic factors (e.g. brain derived neurotrophic factor, BDNF) also contribute to the pathogenesis of anxiety and depression." (PMID 33117172, 2020). "Similarly, BDNF elevation is yet another mechanism of DBD against comorbid depression and diabetes." (PMID 33568996, 2020). "This might have contributed to a lack of association between BDNF levels and general depression symptom severity levels." (PMID 32372985, 2020). "In CUMS-induced spontaneous diabetic rats, DBD (4.0 g/kg) and its main active ingredient ferulic acid (1.36 mg/kg) could increase serum and hippocampal BDNF levels to improve depression-like behavior, an effect that might relate to the activation of the CREB/TrkB signaling pathway." (PMID 33568996, 2020). "Furthermore, MT can suppress the release of glutamate and decrease the inhibitory activity of glutamate on brain-derived neurotrophic factor to lower damage in the neurons of hippocampus, improving cognitive function of major depressive disorder (MDD) patients." (PMID 32655450, 2020). "Since low BDNF levels were associated with self- reported anhedonia across these conditions, BDNF and anhedonia might reflect transdiagnostic aspects involved in AUD and depression." (PMID 32372985, 2020). "Interestingly, miR-206 and miR-155 were shown to directly regulate BDNF in depression studies." (PMID 33029119, 2020). "Although there are several hypotheses concerning the pathophysiology of depression, such as the idea that depression arises from an aminergic neuron disorder, hypercorticosteroidemia due to chronic stress, or insufficiency of BDNF, the mechanistic events in depression remain to be determined." (PMID 33321691, 2020). "Furthermore, the correlation between depression-related behavior and BDNF expression levels was analyzed and we found that sucrose preference (SPT) (p = 0.017), latency (NSFT) (p = 0.012), and immobility (FST) (p = 0.003) were significantly correlated with total Bdnf mRNA in the mPFC." (PMID 32532322, 2020).
depression (continued). "Moreover, stress-induced deficits in structural and synaptic plasticity may be reversed by up-regulation of BDNF, enhancing cognitive flexibility and resilience against depression." (PMID 32231570, 2020). "In an animal model of depression, chronic delivery of (Fucus vesiculosus) fucoidan inhibited clinical signs, blocked the increase in tyrosine hydroxylase expression in the localized areas of the brain and inhibited the decrease in BDNF mRNA expression in the hippocampus." (PMID 32121066, 2020). "Some clinical researches also evidenced this association between the BDNF Met carrier and lower BDNF levels in the patients with major depressive disorder, schizophrenia, and bipolar disorder respectively, indicating BDNF Met carrier may play a vital role in regulating BDNF protein expression." (PMID 33047489, 2020). "The majority of research on the medial prefrontal cortex (mPFC) has shown a correlation between decreased BDNF and anxiety- and depression-like behaviors, while the VTA–PFC projection implies that the upregulation of BDNF in the mPFC may be responsible for other phenotypes related to reward." (PMID 32085670, 2020). "However, further studies are required to investigate the effects of acupuncture on miRNA expression in depression, as acupuncture could target BDNF and related plasticity mechanisms." (PMID 33029119, 2020). "Hence, it is possible that depression and neurodegenerative diseases could be improved by a common neuroplasticity mechanism by regulating BDNF expression." (PMID 33029119, 2020). "The present study was undertaken to test whether the known polymorphisms SLC1A3 C3590T, SLC1A3 C869G and BDNF G196A are associated or not with stress or depression in an eastern Indian population." (PMID 32171272, 2020). "The observed benefits of AE may be mechanistically explained by regulation of glutamatergic system, the neurotoxic effects of HCY in regulating ionotropic glutamate receptors involved in the pathogenesis of depression, and/or influences in glucocorticoids-BDNF expression interaction." (PMID 33374661, 2020). "Additionally, previous research has indicated that miR-124 can serve as a biomarker to diagnose depression, and that the inhibition of miR-124 may help relieve depression by way of regulating the BDNF-TrkB signaling pathway." (PMID 33575257, 2020). "Due to the neurotrophic effects of BDNF we generally hypothesized a positive correlation between sBDNF and cortical estimates, modified due to the reduction of sBDNF and regional gray matter volume/cortical thickness in depressive disorders." (PMID 32883977, 2020). "Thus, MS during early life could generate long-term impacts on the expression of upstream relative protein of BDNF in the hippocampus of rats during adulthood, which coincided with their depression-like behavior." (PMID 30984042, 2019). "In addition, preclinical and clinical evidence suggest that patients with depression tend to present lower levels of serum BDNF when compared to healthy individuals, which may be reversed after antidepressant drug treatment." (PMID 31231276, 2019). "In addition, we hypothesize that volunteers treated with ayahuasca could present higher levels of serum BDNF than those treated with placebo and this BDNF levels would predict the improvements observed in depression severity." (PMID 31231276, 2019). "Thus, we propose that epistasis between HTR1A and BDNF is a control element of the serotonergic system and may be involved in neuropsychiatric disorders as depression." (PMID 30664620, 2019). "A secondary hypothesis was whether cognition and depression non-motor symptoms would increase with the presence of Val66Met BDNF polymorphism." (PMID 31197095, 2019). "Notably, the BDNF pathway plays an important role in depression." (PMID 30625977, 2019).
depression (continued). "In conclusion, these findings support the hypothesis that in FM a deteriorated function of cortical inhibition, indexed by a higher SICI parameter, and a lower function of the DPMS, together with higher levels of BDNF indicate that FM has different pathological substrates from depression." (PMID 31105542, 2019). "Moreover, low serum levels of BDNF are correlated with depression in human patients." (PMID 30585393, 2019). "Thus, in addition to other mechanisms, a reduction in BDNF may ultimately be the reason for the development of depression due to stress-induced neuroinflammation." (PMID 31251788, 2019). "In addition to depression, BDNF signaling is also involved in other neurological disorders such as anxiety and epilepsy, suggesting that Rb1 may also be beneficial for treating these diseases; however, this requires further experimental evidence." (PMID 31572200, 2019). "Moreover, the expression of BDNF and its signaling pathway in the prefrontal cortex is significantly decreased, which is helpful for understanding the pathogenesis of diabetes co-morbid with depression." (PMID 32082151, 2019). "Together, these results unify the evidences regarding the anti-depression effects of AR and suggest that AR may have protective roles in antagonizing stress-induced depressive-like behaviors through down-regulation of miR-204 to promote BDNF expression." (PMID 31480771, 2019). "Thus, BDNF seems an important player in the pathophysiology and might be a biomarker for monitoring treatment response in depression." (PMID 30117106, 2019). "Alteration in monoamines (serotonin and noradrenaline), increasing cortisol levels and decreasing levels of brain-derived neurotrophic factor (BDNF), could explain the association between depression and diabetes in some of the abnormalities documented in diabetic patients and animal models." (PMID 32082151, 2019). "Thus, it may be speculated that the depression-like behavior of the MOAP-1−/− mice may be related to the reduced BDNF which in turn blunted the serotonergic stress response in the DRN." (PMID 30003515, 2019). "The results suggested that quercetin could alleviate LPS-induced depression-like behaviors and impairment of learning and memory in rats, the mechanism of which might be involved with regulating the BDNF-related imbalance expression of Copine 6 and TREM1/2 in the hippocampus and the PFC." (PMID 32009956, 2019). "Furthermore, we evaluated the concentration of BDNF, which is one of the markers of depression." (PMID 31330819, 2019). "Therefore, this study investigated serum BDNF levels from a randomized placebo-controlled trial that tested the potential antidepressant effect of a single dose of ayahuasca in treatment-resistant depression." (PMID 31231276, 2019). "Moreover, it was confirmed that the HCE-produced antidepressant-like effect in a corticosterone-induced depression-like model of rats was at least partly mediated by the brain-derived neurotrophic factor and its protein receptor (BDNF-TrkB) signaling in the frontal cortex and hippocampus region." (PMID 31775329, 2019). "The primary aim of this analysis was to explore whether proposed physical and psychological function measures (depression, anxiety, fatigue, and physical functioning) and mechanistic biomarkers (BDNF, HOMA2-IR, and CRP) mediated intervention effects on cognition." (PMID 31605514, 2019). "In addition, HAR has a variety of other pharmacological effects, such as lowering systemic arterial blood pressure and raising pulse pressure, increasing brain-derived neurotrophic factor protein levels in rat hippocampus to prevent depression, and treating cancer." (PMID 30978991, 2019). "The neuroplastic pathway, including CREB, BDNF and its receptor (neurotrophic tyrosine kinase receptor, type 2 [NTRK2]), has a key role to play in the adaptation of the brain to stress, with the variations of these genes highlighted as potential depression risk factors." (PMID 31406011, 2019).